CPNE1 (copine 1)
Description:
Calcium-dependent phospholipid-binding protein that plays a role in calcium-mediated intracellular processes. Involved in the TNF receptor signaling pathway in a calcium-dependent manner. Exhibits calcium-dependent phospholipid binding properties. Plays a role in neuronal progenitor cell differentiation; induces neurite outgrowth via a AKT-dependent signaling cascade and calcium-independent manner. May recruit target proteins to the cell membrane in a calcium-dependent manner. May function in membrane trafficking. Involved in TNF-induced NF-kappa-B transcriptional repression by inducing endoprotease processing of the transcription factor NF-kappa-B p65/RELA subunit. Also induces endoprotease processing of NF-kappa-B p50/NFKB1, p52/NFKB2, RELB and REL.
Synonyms: CPN1; COPN1
Tractability: Antibody: UniProt places it where antibodies can reach, with high confidence; its Gene Ontology location is reachable by antibodies, with high confidence. PROTAC: ubiquitination databases record sites on it; its protein half-life has been measured.
Gene: Protein-coding gene on chromosome 20 (35,626,031 to 35,664,956, reverse strand). Ensembl gene ENSG00000214078.
Subcellular location: Nucleus; Cytoplasm; Cell membrane
Subcellular location (Human Protein Atlas): Nuclear membrane; Nucleoplasm
Pathways (Reactome):
Immune System: Neutrophil degranulation
Metabolism: Glycerophospholipid biosynthesis
Gene Ontology:
Molecular function: calcium ion binding; endopeptidase activity; identical protein binding; NF-kappaB binding; phosphatidylserine binding; protein binding; calcium-dependent phospholipid binding; protein-membrane adaptor activity
Biological process: cellular response to calcium ion; negative regulation of DNA binding; negative regulation of gene expression; negative regulation of non-canonical NF-kappaB signal transduction; neuron projection extension; positive regulation of neuron differentiation; positive regulation of phosphatidylinositol 3-kinase/protein kinase B signal transduction; positive regulation of tumor necrosis factor-mediated signaling pathway; proteolysis; regulation of canonical NF-kappaB signal transduction; glycerophospholipid biosynthetic process; lipid metabolic process; vesicle-mediated transport
Cellular component: cytoplasm; cytosol; extracellular exosome; membrane; nuclear membrane; nucleoplasm; nucleus; plasma membrane; azurophil granule membrane
Genetic constraint (gnomAD): Loss-of-function variants: 52 observed, 64.73 expected, observed/expected ratio (o/e) 0.8, 90% interval 0.64 to 1.01. The upper end of that interval is the gene's LOEUF score, 1.01, which puts it in group 4 of 6, group 1 being the genes least tolerant of losing a copy. Missense variants: 575 observed, 621.17 expected, observed/expected ratio (o/e) 0.93, 90% interval 0.86 to 0.99. Synonymous variants: 199 observed, 234.29 expected, observed/expected ratio (o/e) 0.85, 90% interval 0.76 to 0.95.
Homologues: Orthologues: rabbit CPNE1 (93% identical), pig CPNE1 (93% identical), guinea pig CPNE1 (90% identical), tropical clawed frog cpne1 (71% identical), zebrafish cpne1 (67% identical). Paralogues in human: CPNE3 (66% identical), CPNE2 (58% identical), CPNE7 (52% identical), CPNE4 (51% identical), CPNE8 (51% identical), CPNE5 (50% identical), CPNE6 (50% identical), CPNE9 (47% identical).
Diseases named in the same sentence as CPNE1 in open-access papers:
CPNE1 is named in the same sentence as 40 diseases in open-access papers, as found by Europe PMC text mining. Sharing a sentence is not in itself a finding about the gene and the disease. The quoted sentences say what the papers report.
prostate carcinoma (7 papers, 2018 to 2023). A carcinoma that arises from epithelial cells of the prostate gland. "Recent studies have shown higher CPNE1 expression in prostate cancer and that CPNE1expression is associated with the stage and prognosis of prostate cancer patients." (PMID 34367247, 2021). "CPNE1 is highly expressed in prostate cancer and its expression is positively associated with TRAF2 expression, and is related to advanced tumor stages and poor survival." (PMID 32201531, 2020). "In prostate cancer, CPNE1 proved to be a significant prognostic biomarker for evaluating recurrence-free survival, and was positively correlated with TRAF2 expression." (PMID 37077419, 2023). "Meanwhile, CPNE1 participates in the process of carcinogenesis and development of breast cancer, non‐small cell lung cancer, prostate cancer, liver cancer, thyroid cancer and osteosarcoma." (PMID 35139863, 2022). "CPNE1 is significantly upregulated and plays an oncogenic role in a variety of cancers, including breast cancer, colorectal cancer and prostate cancer." (PMID 35101055, 2022). "In regard to other members of the Copine family, Copine 1 abolishes NF-κB transcription by endoprotease processing of the N-terminus of p65 in human prostate cancer cells." (PMID 31487856, 2019). "Also, CPNE1 is significantly correlated with the tumor stage, Gleason score and recurrence-free survival of prostate cancer and is positively correlated with expression of TRAF2 as a prognostic marker in prostate cancer." (PMID 35139863, 2022). "Mechanistically, CPNE1 interacts with TRAF-2 to promote prostate cancer progression." (PMID 34367247, 2021). "CPNE1 was demonstrated to be up-regulated in osteosarcoma and prostate cancer." (PMID 32201531, 2020). "Finally, a recent research has shown that the expression level of CPNE1 is higher in prostate cancer than in normal prostate tissue." (PMID 29970127, 2018). "The expression of CPNE1 is higher in prostate cancer tissue and castration-resistant prostate cancer tissue than that in normal prostatic tissues and noncastrated-resistant prostate cancer tissue, respectively." (PMID 35139863, 2022). "The present study is the first to report that CPNE1 expression is upregulated and is positively correlated with the TNM stage and lymph node metastasis status in NSCLC patients; this finding is consistent with the results of a study on prostate cancer." (PMID 29970127, 2018).
breast carcinoma (6 papers, 2022 to 2024). "This discovery suggests that a reduction in CPNE1 levels may increase the risk of breast cancer, which contradicts the tumor-promoting role of CPNE1 supported by conventional basic research." (PMID 39351539, 2024). "This causal insight offers a new perspective on CPNE1 as a potential therapeutic target in breast cancer and suggests that future research should further explore the dual mechanisms of CPNE1 to gain a more comprehensive understanding of its role in breast cancer progression." (PMID 39351539, 2024). "Although most foundational studies suggest that CPNE1 has a pro-tumor role in cancer progression, our study and Ren’s research, employing MR, provide robust evidence from a causal perspective that CPNE1 may have a protective role in breast cancer." (PMID 39351539, 2024). "Decreased levels of CASP8, DDX58, CPNE1, ULK3, PARK7, and BTN2A1, as well as increased levels of TNFRSF9, TNXB, DNPH1, and TLR1, were linked to an elevated risk of breast cancer." (PMID 39351539, 2024). "Our findings indicated a negative association between CPNE1 and breast cancer risk (OR: 0.94, 95% CI: 0.90-0.98), and Ren’s study yielded similar results (OR: 0.96, 95% CI: 0.94-0.98)." (PMID 39351539, 2024). "We identified KDEL motif-containing protein 2 (KDELC2) and RCC, as well as Copine-1 (CPNE1) and Immunoglobulin superfamily containing leucine-rich repeat protein 2 (ISLR2) and breast cancer as having a high posterior probability of a shared variant (i.e. PPH4 > 0.8)." (PMID 38527997, 2024). "Furthermore, we observed an inverse association between CPNE1 (OR: 0.96, 95% CI 0.94–0.98) and breast cancer, while PDIA3 (OR: 1.19, 95% CI 1.10–1.30) were found to be associated with the risk of breast cancer." (PMID 37735436, 2023). "CASP8, DDX58, CPNE1, ULK3, PARK7, and TNFRSF9 have already been identified as targets in drug development and potential therapeutic targets for breast cancer treatment." (PMID 39351539, 2024). "Similar results were obtained for the two latter genes in the enrichment analysis using Metascape, which also highlighted the involvement of CPNE1 and PLXNA1 in breast cancer." (PMID 38184718, 2024).
lung cancer (6 papers, 2018 to 2023). A malignant neoplasm involving the lung. "Previous studies showed that CPNE1 is a critical factor in the tumorigenesis of lung cancer and that its mechanism involves the EGFR signaling pathway." (PMID 37077419, 2023). "Only 3 articles have reported the study of CPNE1 in lung cancer, and all were written by our research group." (PMID 35101055, 2022). "Taken together, these results confirm that the CPNE1 protein is degraded by both the ubiquitin-proteasome pathway and the lysosomal pathway in lung cancer cells." (PMID 34743202, 2021). "To further characterize the regulation of NEDD4L-induced CPNE1 upregulation in lung cancer cells, we established stable NEDD4L knockout (NEDD4L KO) A549 cell lines." (PMID 34743202, 2021). "NEDD4L knockout stabilized the CPNE1 protein and enhanced the proliferation and metastasis of lung cancer cells." (PMID 34743202, 2021). "We also characterized the suppressive role of CPNE1 in cell motility, highlighting a new molecular function and cancer phenotype regulated by miR‐335 and CPNE1 in lung cancer." (PMID 34977878, 2021). "CPNE1 was highly expressed in lung cancer and was positively correlated with TNM stage and lymph node metastasis." (PMID 34743202, 2021). "Here, our study newly reported an oncogenetic role of miR‐335 in lung adenocarcinoma, by which miR‐335 enhances migratory and invasive abilities of lung cancer cells via targeting copine‐1 (CPNE1), an NF‐κB signaling suppressor." (PMID 34977878, 2021). "We found that the expression of CPNE1 in lung cancer cell lines (A549, H226, H1299, H1650, SPC-A1, HCC827, and H460) was higher than that in a normal lung epithelial cell line (BEAS-2B) using Western blotting and qRT-PCR." (PMID 34743202, 2021). "To elucidate the specific mechanism of the high expression of CPNE1 in lung cancer, we studied its regulation at the pre-transcriptional level." (PMID 34743202, 2021). "A lung carcinoma xenograft mouse model was used to investigate the in vivo effects of CPNE1 overexpression." (PMID 29970127, 2018). "In lung cancer, CPNE1 acts as a target of miR-335-5p, and the inhibition of CPNE1 could enhance the clinical efficacy of EGFR-tyrosine kinase inhibitors." (PMID 37077419, 2023). "Although the role of miR‐335 and CPNE1 we revealed in lung cancer was contrary to previous findings, it is interesting to ask whether the molecular function of miR‐335 and CPNE1 depends on any specific condition." (PMID 34977878, 2021). "In the current study, we reveal that CPNE1 repression by miR-335-5p inhibits cell growth and metastasis in NSCLC cells via modulation of the EGFR signaling pathway, and establish the mechanistic interaction between CPNE1 and miR-335-5p in regulation of the lung cancer cell phenotype." (PMID 29970127, 2018). "Overexpression of CPNE1 can activate Src, FAK, AKT, ERK, and other signaling pathways in vivo and promote the proliferation and metastasis of lung cancer cells." (PMID 34743202, 2021). "Our previous study found that high expression of CPNE1 was positively correlated with TNM stage, lymph node metastasis, and distant metastasis in 128 lung cancer tissues." (PMID 34743202, 2021). "Thus, miR-335-5p may be involved in lung cancer progression via the regulation of CPNE1." (PMID 29970127, 2018). "CPNE1 may regulate growth, migration and invasion of lung adenocarcinoma cells through AKT and ERK pathways, which could promote nonsmall-cell lung cancer progression." (PMID 35139863, 2022). "We further investigated the localization of CPNE1 and NEDD4L in lung cancer cells." (PMID 34743202, 2021).
lung adenocarcinoma (5 papers, 2018 to 2022). A carcinoma that arises from the lung and is characterized by the presence of malignant glandular epithelial cells. "High expression of Copine 1 is also associated with cell growth and metastasis in lung adenocarcinoma." (PMID 31487856, 2019). "The expression of CPNE1 is associated with TNM staging, lymph node metastasis and distant metastasis of lung adenocarcinoma." (PMID 35139863, 2022). "Then, analysis of the TCGA database showed that CPNE1 was highly expressed in NSCLC, both in lung adenocarcinoma and lung squamous cell carcinoma." (PMID 34743202, 2021). "In addition, miR-195-5p is responsible for the ability of high CPNE1 expression to result in poor prognosis in squamous cell lung cancer (SCC) and lung adenocarcinoma (ADC)." (PMID 34743202, 2021).
non-small cell lung carcinoma (5 papers, 2018 to 2022). A group of at least three distinct histological types of lung cancer, including non-small cell squamous cell carcinoma, adenocarcinoma, and large cell carcinoma. "CPNE1 was a target of miR-335–5 and CPNE1 silencing could effectively improve clinical responses of EGFR-tyrosine kinase inhibitors (TKIs) in non-small cell lung cancer." (PMID 35139863, 2022). "Our previous studies revealed that oncogene CPNE1 is positively correlated with the occurrence, TNM stage, lymph node metastasis, and distant metastasis of non-small-cell lung cancer (NSCLC), and it could be regulated by micro RNAs." (PMID 34743202, 2021).
liver cancer (4 papers, 2011 to 2024). An epithelial or non-epithelial malignant neoplasm that arises from the liver. "CPNE1 is linked to chromosome deletion of 13q in hepatic carcinoma cells and mediates the process of occurrence and progression by regulating the dedifferentiation, cell cycle and proliferation in liver cancer." (PMID 35139863, 2022). "It has mentioned that CPNE1 mediates the process of progression by regulating the dedifferentiation, cell cycle and proliferation in liver cancer." (PMID 35139863, 2022). "CPNE1 gene regulates tumour necrosis factor-alpha receptor signaling pathway and is over-expressed in liver cancer, but is still poorly investigated in CRC tumorigenesis." (PMID 21645411, 2011).
colorectal cancer (3 papers, 2022 to 2024). A primary or metastatic malignant neoplasm that affects the colon or rectum. "The overexpression of CPNE1 in tumors has been implicated in promoting the progression of colorectal cancer and metastasis." (PMID 38544823, 2024). "This was thus achieved with supporting results of the high expression of germline variants in CTSB, and CPNE1 predicted in colorectal cancer." (PMID 38544823, 2024). "With some of these results corroborating the outcomes of the present study, our study implicates CTSB and CPNE1 as important colorectal cancer indicators and suggests further experimental validation and comprehensive analysis for prospective studies." (PMID 38544823, 2024). "In colorectal cancer, CPNE1 increased aerobic glycolysis via regulating AKT-GLUT1/HK2 pathway, and contributed to chemoresistance." (PMID 37077419, 2023). "CPNE1 is able to regulate glycolysis, and promote colorectal cancer cell growth and drug resistance through AKT-GLUT1/HK2 pathway." (PMID 37077419, 2023). "From this analysis, it is understood that two genes, CTSB and CPNE1, may tend to be more active in colorectal cancer cases than any other, implying further analysis into its use as a cancer indicator." (PMID 38544823, 2024).
triple-negative breast carcinoma (3 papers, 2021 to 2024). An invasive breast carcinoma which is negative for expression of estrogen receptor (ER), progesterone receptor (PR), and human epidermal growth factor receptor 2 (HER2). "However, multiple studies have also shown that CPNE1 promotes aerobic glycolysis and metastasis in triple-negative breast cancer (TNBC) through the PI3K/AKT/HIF-1α signaling pathway, thereby accelerating tumor progression." (PMID 39351539, 2024). "Another study showed that CPNE1 promotes tumorigenesis and radioresistance in triple-negative breast cancer by regulating AKT activation, and targeted CPNE1 expression may be a strategy to sensitize triple-negative breast cancer cells to radiation therapy." (PMID 34367247, 2021). "CPNE1 may promote tumorigenesis and radioresistance of triple-negative breast cancer (TNBC) through AKT pathway activation and so target expression of CPNE1 could be a good strategy to sensitize TNBC to radiotherapy." (PMID 35139863, 2022).
diabetes (2 papers, 2021 to 2023). "The differential expression of CPNE1 is more often associated with poor prognosis in diseases such as cancer and diabetes." (PMID 36525128, 2023).
epithelial ovarian cancer (2 papers, 2021 to 2025). "In ovarian cancer, CPNE1 is significantly upregulated and associated with poor prognosis." (PMID 40330466, 2025). "Thus, CPNE1’s role in macrophage polarization supports ovarian cancer progression and makes it a potential therapeutic target." (PMID 40330466, 2025). "Copine 1 (CPNE1) is a calcium-dependent, membrane-binding protein that plays a critical role in promoting tumor progression in various cancers, including ovarian cancer." (PMID 40330466, 2025).
gastric cancer (2 papers, 2023 to 2024). A primary or metastatic malignant neoplasm involving the stomach. "CPNE1 influenced cell proliferation, cytochrome c-mediated caspase cascade apoptosis and arrested cell cycle in gastric cancer via DDIT3-FOS-MKNK2 axis." (PMID 37077419, 2023).
lung squamous cell carcinoma (2 papers, 2020 to 2021). "Moreover, among the different subtypes, patients with squamous cell lung cancer (SCC) exhibited higher level of CPNE1 expression, as well as substantially poorer survival." (PMID 32201531, 2020).
osteosarcoma (2 papers, 2020 to 2022). A usually aggressive malignant bone-forming mesenchymal neoplasm, predominantly affecting adolescents and young adults. "In addition, CPNE1 silencing can inhibit osteosarcoma cell proliferation, invasion, and migration, suggesting a potential target for osteosarcoma therapy." (PMID 32201531, 2020).